SAMHD1 (SAM and HD domain containing deoxynucleoside triphosphate triphosphohydrolase 1)
Diseases named in the same sentence as SAMHD1 in open-access papers (continued):
Sharing a sentence is not in itself a finding about the gene and the disease.
mantle cell lymphoma (6 papers, 2021 to 2025). Mantle cell lymphoma is a rare form of malignant non-Hodgkin lymphoma affecting B lymphocytes in the lymph nodes in a region called the ``mantle zone''. "In total, 1 542 SAMHD1 mutations have been identified in various cancer types, including chronic lymphocytic leukemia, mantle cell lymphoma, and colorectal cancer." (PMID 37009792, 2023). "Only recently, mutations in SAMHD1 were also detected in 7.1% (13/182) of mantle cell lymphoma (MCL) patients selected from the MCL Younger and Elderly trials; of note, both cohorts only included previously untreated patients." (PMID 34480199, 2022). "SAMHD1 promotes chemoresistance because, given the structural similarity to endogenous dNTP, the nucleotide analogs used for acute myeloid leukemia and mantle cell lymphoma treatments are degraded by SAMHD113–15." (PMID 37009792, 2023). "SAMHD1 was also reported as a barrier to cytarabine, a common chemotherapy drug for mantle cell lymphoma (MCL), and as a biomarker of grim prognosis for acute myelocytic leukemia (AML) patients." (PMID 34976810, 2021). "Additionally, the endogenous SAMHD1 inhibitor SOX11 has been identified as a therapeutic target in mantle cell lymphoma (MCL)." (PMID 41267084, 2025). "Low frequency (<10% or < 25%) of SAMHD1+ mantle cell lymphoma cells did not predict PFS, nor did the median (60%) or a 75% cutoff (all P > 0.5)." (PMID 34738194, 2022).
prostate carcinoma (6 papers, 2024 to 2026). A carcinoma that arises from epithelial cells of the prostate gland. "SAMHD1 has recently been identified as associated with prostate cancer, with rare mutations carrying a very high risk." (PMID 41516419, 2026). "At the gene level, our case-control collapsing analysis confirms associations between rare damaging variants in four genes and increased prostate cancer risk: SAMHD1, BRCA2 and ATM at the study-wide significance level (P < 1×10−8), and CHEK2 at the suggestive threshold (P < 2.6×10−6)." (PMID 39971927, 2025). "Two recently published studies identified several genes—BIK, SAMHD1, FAM111A, AOX1, among others—in which rare variants are significantly and strongly associated with increased risk of prostate cancer (PCa) and its aggressiveness." (PMID 40825105, 2025).
AIDS (4 papers, 2012 to 2024). A syndrome resulting from the acquired deficiency of cellular immunity caused by the human immunodeficiency virus (HIV). "Notably, despite HIV-1 being the primary pathogen responsible for global AIDS, its inability to encode the Vpx protein hampers its capacity to overcome the antiviral defense by SAMHD1 in macrophages." (PMID 38888311, 2024). "Deciphering the functional interaction between HIV-1 and SAMHD1 will lead to a better understanding of the damage imposed by this virus to the immune system and the progression towards AIDS." (PMID 23092122, 2012). "SAMHD1-mediated HIV-1 restriction in resting CD4+ T-lymphocytes might be important for AIDS immunopathogenesis." (PMID 24523981, 2013). "The demonstration that SAMHD1 restricts HIV-1 replication in quiescent CD4+ T-cells could have an important implication in our understanding of HIV-1-mediated CD4+ T-cell depletion and establishment of the viral reservoir, two of the HIV/AIDS hallmarks." (PMID 23092122, 2012). "We found, however, that this is not the case because Vpx-mediated degradation of SAMHD1 was preserved in all biological viral clones derived from seven HIV-2-infected individuals that developed high viral loads and progressed to AIDS." (PMID 23497283, 2013). "We found that effective Vpx-mediated SAMHD1 degradation and enhancement of myeloid cell infection was preserved in most HIV-2-infected individuals including all seven that failed to control the virus and developed AIDS." (PMID 23497283, 2013).
cerebrovascular disease (4 papers, 2015 to 2023). "SAMHD1 probably plays a protective role in preventing self-activation of innate immunity, and mutations of this gene predispose patients to cerebrovascular disease through immune etiology." (PMID 36650407, 2023). "There are several classic AGS subtypes with prenatal and infantile-onset: spastic-dystonic syndrome, ADAR-1-related bilateral striatal necrosis, hereditary spastic paraparesis, and SAMHD-1-related cerebrovascular disease." (PMID 37371788, 2023). "No patients with bilateral striatal necrosis, hereditary spastic paraparesis, and SAMHD1-related cerebrovascular disease were reported in our study." (PMID 35551623, 2022). "Indeed, AGS genes were recognized as being associated with phenotypes different from classic AGS, such as ADAR1-related bilateral striatal necrosis (BSN), hereditary spastic paraplegia, and SAMHD1-related cerebrovascular disease." (PMID 36650407, 2023).
cervical carcinoma (4 papers, 2020 to 2024). A carcinoma arising from either the exocervical squamous epithelium or the endocervical glandular epithelium. "Here, we demonstrate that in HPV-negative cervical cancer C33a cells and human foreskin keratinocytes immortalized by HPV16 (HFK+HPV16), SAMHD1 is recruited to E1-E2 replicating DNA." (PMID 39194246, 2024).
co-infection (4 papers, 2017 to 2025). "When MDMs were exposed to LPS and infected with HIV-1, only cells where SAMHD1 was exogenously depleted by co-infection with SIV VLP WT were fully susceptible to infection." (PMID 32209460, 2020).
cutaneous T-cell lymphoma (4 papers, 2015 to 2022). "Initially, it was reported that SAMHD1 mRNA and protein expression were reduced in peripheral blood mononuclear cells (PBMCs) obtained from patients with Sézary syndrome (SS), an aggressive subtype of cutaneous T-cell lymphoma (CTLC), compared to healthy donors." (PMID 34480199, 2022).
glioma (4 papers, 2022 to 2026). A benign or malignant brain and spinal cord tumor that arises from glial cells (astrocytes, oligodendrocytes, ependymal cells). "Other gene functions implicated in glioma risk in this study include signal transduction (e.g. EGFR), cell adhesion (e.g. GJB2), immune response (e.g. IFIH1 and SAMHD1), and ion transport (e.g. CFTR)." (PMID 41546701, 2026). "Potential glioma risk genes with a pathogenic GV most frequently played roles in cell adhesion (CTNND1, EPCAM), immune response (IFIH1, SAMHD1), and ion transport (SLC4A7, TRPM1)." (PMID 41546701, 2026). "Furthermore, the lower-grade glioma cell line (H4) that displayed reduced SAMHD1 expression compared to LN-229 tolerated VLP(+Vpx) exposure, achieving gID50 at 5μg/mL." (PMID 36139652, 2022). "Interestingly, when dividing gliomas based on this classification, IDH WT gliomas expressed significantly higher SAMHD1 levels than IDH mut-codel, the least aggressive glioma." (PMID 36139652, 2022). "The ANOVA yielded a significant p-value of 0.018, and in a pair-wise comparison with Tukey-Kramer’s post-hoc test, samples obtained from GBM patients showed a significantly elevated SAMHD1 level compared to both lower-grade gliomas and non-tumor brain samples." (PMID 36139652, 2022). "In contrast, other types of cancers, such as glioma, uterine corpus endometrial carcinoma, and especially pankidney cancer, had much greater SAMHD1 mRNA levels in tumor tissues than in nontumor tissues, indicating that SAMHD1 serves as a tumor suppressor or oncogene depending on the type of cancer." (PMID 37009792, 2023).
hepatocellular carcinoma (4 papers, 2016 to 2025). A malignant tumor that arises from hepatocytes. "Emerging evidence suggests that the sterile alpha‐motif (SAM) and histidine‐aspartate (HD) domain‐containing protein 1 (SAMHD1) is implicated in various cancers, including hepatocellular carcinoma (HCC)." (PMID 39679869, 2025). "We attempted to elucidate the underlying mechanisms by which SAMHD1 affects the proliferation of hepatoma cells." (PMID 39679869, 2025). "Taken together, our findings uncovered a novel mechanism by which SAMHD1 restricts hepatoma cell proliferation, exerting control over cell mitosis progression through the modulation of cohesin dynamics." (PMID 39679869, 2025). "Collectively, our study has found a novel anti‐tumor mechanism of nuclear SAMHD1 in hepatoma cells, mediated by the prolongation of M phase through enhanced chromatid cohesion." (PMID 39679869, 2025). "Our study uncovers that nuclear SAMHD1 plays a protective role in slowing down HCC progression, supported by data showing that nuclear overexpression of SAMHD1 in hepatoma cells inhibits cell proliferation and migration." (PMID 39679869, 2025). "To investigate the role of nuclear SAMHD1 in the proliferation and migration of hepatoma cells, we overexpressed SAMHD1 with its nuclear localization sequence in HepG2 and Huh7 cells." (PMID 39679869, 2025). "Mechanistic studies further demonstrated that nuclear SAMHD1 overexpression restricts hepatoma cell proliferation by increasing sister chromatid cohesion, which leads to M phase stalling." (PMID 39679869, 2025). "The wound healing and transwell assays demonstrated that nuclear SAMHD1 overexpression inhibited the migration of hepatoma cell lines." (PMID 39679869, 2025). "Second, using Samhd1 KO hepatoma cells, we observed a significant 1–2 log increase in newly synthesized and secreted HBV DNA particles." (PMID 30918010, 2019). "This study uncovers the key role for nuclear SAMHD1 in slowing hepatocellular carcinoma (HCC) progression." (PMID 39679869, 2025). "Moreover, we discovered a new mechanism of SAMHD1 in tuning the cell cycle of hepatoma cells, which might be a new therapeutic strategy to restrain tumor progression by mediating cohesin complex dynamics during cell mitosis." (PMID 39679869, 2025). "In line with reports that SAMHD1 restricts HIV replication, we confirm a significant increase in HIV RT-dependent replication in our Samhd1 KO hepatoma cells." (PMID 30918010, 2019). "In hepatoma cell lines, nuclear overexpression of SAMHD1 inhibited cell proliferation by stalling mitosis, independent of its deoxynucleotide triphosphohydrolase (dNTPase) function." (PMID 39679869, 2025).
Sézary syndrome (4 papers, 2018 to 2024). "Indeed, SAMHD1 is implicated in Sézary syndrome, a type of T-cell lymphoma, for which there is an inverse association between SAMHD1 expression and malignancy." (PMID 39206868, 2024). "Additionally, increased expression of all microRNA-181 family members (a-d) was detected in primary CD4+ T-cells from Sézary syndrome patients compared to healthy control cells, which was again associated with reduced SAMHD1 protein expression." (PMID 34480199, 2022). "Thus, the situation in T-PLL is different from that of CD4 T cells of patients with Sézary syndrome in which the SAMHD1 promotor is hypermethylated." (PMID 29352181, 2018).
ZIKV infection (4 papers, 2019 to 2024). "The proviral role of SAMHD1 in Zika virus infection of human skin cells is likely due to its dNTPase activity, which reduces the level of dNTPs, thus potentially increasing the NTP pool for RNA viruses." (PMID 39339888, 2024). "Together, these data demonstrate that degradation of SAMHD1 by SIV Vpx inhibits CHIKV and ZIKV infection and that SAMHD1 impacts at least one of post-entry step of the CHIKV infection cycle." (PMID 30959732, 2019). "The results from the SILAC/MS analysis showed significantly increased expression of SAMHD1 in HFF1 cells following both CHIKV or ZIKV infection." (PMID 30959732, 2019). "These included MX1, IFIT1, ISG15, SAMHD1, IFIT3, and STAT1, all of which have been shown to be similarly upregulated by ZIKV infection in other human cell types, including fibroblasts and pluripotent stem cell (iPSC)-derived neural progenitor cells (NPC), as also demonstrated by LC-MS/MS analysis." (PMID 34079533, 2021).
acute monocytic leukemia (3 papers, 2020 to 2024). Acute monoblastic leukemia (AML-M5), is one of the most common subtypes of acute myeloid leukemia (AML) that is either comprised of more than 80% of monoblasts (AML-M5a) or 30-80% monoblasts with (pro)monocytic differentiation (AML-M5b). "However, another study has demonstrated that SAMHD1 knock-out ThP1 cell, a human monocytic cell line derived from an acute monocytic leukemia patient, exhibited an increased proliferation." (PMID 36139652, 2022). "To investigate the impact of TRIM21‐mediated degradation of SAMHD1 on HIV‐1 infection, we employed THP‐1 cells, a human cell line derived from the peripheral blood of an acute monocytic leukemia patient that can be differentiated with phorbol esters (PMA)." (PMID 31797533, 2020).
Encephalopathy (3 papers, 2020 to 2026). Encephalopathy is a term that means brain disease, damage, or malfunction. "If biallelically mutated, IFIH1 and SAMHD1 are among the genes causing the autosomal recessive Aicardi-Goutières syndrome (AGS), a type I interferonopathy leading to an early-onset progressive encephalopathy with basal ganglia calcifications." (PMID 41546701, 2026).
Immunodeficiency (3 papers, 2015 to 2026). Failure of the immune system to protect the body adequately from infection, due to the absence or insufficiency of some component process or substance. "It remains unclear whether the genetic loss of SAMHD1 in AGS is corelated with cancers, mainly because of the rare incidence and early death of patients with this severe immune disorder." (PMID 34492268, 2021). "This need to degrade SAMHD1 during SIV infections of memory CD4+ T cells in vivo selects for Vpx revertant viruses capable of generating high levels of plasma viremia and inducing immunodeficiency." (PMID 25996507, 2015).
lymphoma (3 papers, 2015 to 2022). A malignant (clonal) proliferation of B- lymphocytes or T- lymphocytes which involves the lymph nodes, bone marrow and/or extranodal sites. "To validate the importance of the selected cutoff point of ≥90% SAMHD1 positive lymphoma cells, we obtained samples and clinical data from the MCL2 and MCL3 trials (ASCT validation cohort, N = 91)." (PMID 34738194, 2022). "Twenty-two out of 91 (24%) patients had ≥90% SAMHD1 positive lymphoma cells." (PMID 34738194, 2022). "However, patients with ≥90% SAMHD1 positive lymphoma cells had shorter PFS and OS." (PMID 34738194, 2022). "Dual staining for CD20 and SAMHD1 in MCL revealed a high variability in the frequency of SAMHD1 positive cells in MCL, and that the intensity of SAMHD1 positivity in MCL nuclei was, with the exception of a few cases, lower than in the lymphoma infiltrating reactive T cells and macrophages." (PMID 34738194, 2022).
melanoma (3 papers, 2020 to 2022). A malignant, usually aggressive tumor composed of atypical, neoplastic melanocytes. "Only the module turquoise had a significant enrichment (p = 0.009) of genes whose homologs displayed prognostic value in melanoma, such as Oca2, Samhd1, Nlrc5, Irf1, Ifitm3, Sp100, Dram1, Rtn1, Tcaf2, Parp10, and Grin3a." (PMID 32831131, 2020). "As SAMHD1 expression was undetectable in a subset of CCLE melanoma cell lines, we extended our analysis to a panel of melanoma cell lines derived at UCLA." (PMID 35653193, 2022).
ovarian carcinoma (3 papers, 2022 to 2025). A malignant neoplasm originating from the surface ovarian epithelium. "Here, we provide evidence of the involvement of SAMHD1 in the induction and modulation of anti-tumoral immunity in ovarian cancer." (PMID 36845138, 2023). "In view of the promising pre-clinical data, we evaluated the role of SAMHD1 in 22 ovarian cancer patients." (PMID 36845138, 2023). "SAMHD1 expression was downregulated in ovarian cancer cell lines OVCAR3 and SKOV3 by RNA interference." (PMID 36845138, 2023). "SAMHD1 expression in ovarian cancer patients was evaluated by immunohistochemistry and survival analysis was performed according to SAMHD1 expression." (PMID 36845138, 2023). "In conclusion, our data provides evidence of the involvement of SAMHD1 in ovarian cancer, as previously reported in other cancer types." (PMID 36845138, 2023). "Next steps should aim to validate these results in larger series, as well as prospectively explore the correlation between SAMHD1 expression, innate immune response, and inflammatory chemokines directly in ovarian cancer patients." (PMID 36845138, 2023). "To determine the contribution of SAMHD1 in ovarian cancer, we effectively downregulated SAMHD1 expression in the ovarian cancer cell lines OVCAR3 and SKOV3, leading to a 70-80% reduction in SAMHD1 RNA and protein expression levels." (PMID 36845138, 2023). "Similar results were obtained in ovarian cancer cells after effective know-down of SAMHD1 by RNA interference, showing increased DNA damage and apoptosis upon SAMHD1 depletion an effect that was further enhanced upon treatment with platinum derivatives." (PMID 35158911, 2022). "In ovarian carcinoma samples, those with high grade serous papillary ovarian carcinoma were the most positive for SAMHD1 (p = 0.028)." (PMID 35158911, 2022). "Conversely, SAMHD1 knockdown increases apoptosis in ovarian cancer cell lines." (PMID 40434097, 2025). "Thus, here we evaluated the role of SAMHD1 expression and function in ovarian cancer in vitro and in patient cohorts." (PMID 36845138, 2023). "Here, we evaluate SAMHD1 function in ovarian cancer, both in vitro and in ovarian cancer patients." (PMID 36845138, 2023). "SAMHD1 depletion correlates with increased innate immune cell signalling in ovarian cancer cells." (PMID 36845138, 2023). "Overall, clinical data allowed us to propose SAMHD1 as a prognostic marker in ovarian cancer, whose function might putatively induce antitumoral innate immune response, as demonstrated in vitro in cell lines." (PMID 36845138, 2023). "Overall, clinical data allow us to propose SAMHD1 as a prognostic marker in ovarian cancer, whose function might putatively induce antitumoral proinflammatory innate immune response, as demonstrated in vitro in cell lines." (PMID 36845138, 2023). "Moreover, low SAMHD1 expression is a positive predictive factor in lung and ovarian cancer treated with platin derivates and/or antimetabolites." (PMID 35158911, 2022). "Median OSCD was 157 months in SAMHD1 negative in front of 62 months in SAMHD1 positive, for ovarian cancer patients (log rank function, p = 0.040)." (PMID 35158911, 2022). "Ovarian carcinoma patients showed a median DFS of 52 months for SAMHD1 negative patients in front of 11 months for SAMHD1 positive patients (p = 0.005)." (PMID 35158911, 2022).
pancreatic cancer (3 papers, 2020 to 2022). "Our study included 98 advanced cancer cases of high incident and/or high mortality tumors such as NSCLC, breast, ovarian, and pancreatic cancers, on which SAMHD1′s role has been extensively evaluated." (PMID 35158911, 2022). "Conversely, knocking out SAMHD1 in SUIT2 pancreas cancer cells rendered them hypersensitive to the dCK-dependent lethality of PNPi/dG." (PMID 35653193, 2022). "Considering the lack of variability in SAMHD1 expression levels among rectal and pancreatic cancer cases, these two cancer types were excluded from further analysis, as the absence of a control arm made it impossible to evaluate SAMHD1 function in these tumor types." (PMID 35158911, 2022).
psoriasis (3 papers, 2020 to 2023). An autoimmune condition characterized by red, well-delineated plaques with silvery scales that are usually on the extensor surfaces and scalp. "SAMHD1, C10orf99, and AKR1B10: the highly dysregulated genes in resolved epidermis are known to be associated with pathogenesis of psoriasis, and the DRTP was enriched in WNT, TNF, and mTOR signaling pathways." (PMID 36901987, 2023).
T-cell prolymphocytic leukemia (3 papers, 2018 to 2022). A slow-growing type of leukemia (blood cancer) in which too many lymphocytes are found in the bone marrow and/or blood. "Apart from being recurrently mutated in rCLL, SAMHD1 mutations were also found in 18% of patients with T-cell prolymphocytic leukemia (T-PLL)." (PMID 34480199, 2022).